SCARNA22 (small Cajal body-specific RNA 22)
Synonyms: ACA11
Gene: Small Cajal body-specific RNA gene on chromosome 4 (1,974,636 to 1,974,760, forward strand). Ensembl gene ENSG00000249784.
Gene Ontology:
Biological process: RNA processing
Cellular component: Cajal body; nucleolus
Homologues: Orthologues: chimpanzee SCARNA22 (100% identical), macaque SCARNA22 (98% identical). Paralogues in human: SCARNA23 (35% identical).
Diseases named in the same sentence as SCARNA22 in open-access papers:
SCARNA22 is named in the same sentence as 7 diseases in open-access papers, as found by Europe PMC text mining. Sharing a sentence is not in itself a finding about the gene and the disease. The quoted sentences say what the papers report.
nasopharyngeal carcinoma (1 paper, 2023). A carcinoma arising from the nasopharyngeal epithelium. "Furthermore, we screened five up-regulated lncRNAs (LOC100144603, RP11-545G3.1, SCARNA22, TAZ, and TIMM8B) and six down-regulated lncRNAs (AC003986.7, AK055386, BC013821, DQ786304, LOC647979 and RP11-179H18.2) in nasopharyngeal carcinoma specimens." (PMID 37710236, 2023).
SCARNA22 also shares sentences with these, for which no sentence is quoted: multiple myeloma (6 papers); tumor (2); Autoimmunity (1); cancer (1); leukemia (1); prostate carcinoma (1).